FBP2 (fructose-bisphosphatase 2)
Description:
Catalyzes the hydrolysis of fructose 1,6-bisphosphate to fructose 6-phosphate in the presence of divalent cations and probably participates in glycogen synthesis from carbohydrate precursors, such as lactate.
Synonyms: CORLK
Tractability: Small molecule: a structure with a bound ligand is known. Antibody: its Gene Ontology location is reachable by antibodies, with high confidence. PROTAC: its protein half-life has been measured.
Gene: Protein-coding gene on chromosome 9 (94,558,720 to 94,593,824, reverse strand). Ensembl gene ENSG00000130957.
Subcellular location: Cell junction; Cytoplasm; Nucleus; Cytoplasm, myofibril, sarcomere, Z line
Subcellular location (Human Protein Atlas): Cytosol; Plasma membrane
Pathways (Reactome):
Metabolism: Gluconeogenesis
Gene Ontology:
Molecular function: identical protein binding; protein binding; fructose 1,6-bisphosphate 1-phosphatase activity; phosphatase activity; phosphoric ester hydrolase activity
Biological process: fructose metabolic process; gluconeogenesis; carbohydrate metabolic process
Cellular component: cytosol; extracellular exosome; anchoring junction; cytoplasm; nucleus; Z disc
Genetic constraint (gnomAD): Loss-of-function variants: 25 observed, 31.76 expected, observed/expected ratio (o/e) 0.79, 90% interval 0.57 to 1.1. The upper end of that interval is the gene's LOEUF score, 1.1, which puts it in group 4 of 6, group 1 being the genes least tolerant of losing a copy. Missense variants: 390 observed, 417.83 expected, observed/expected ratio (o/e) 0.93, 90% interval 0.86 to 1.01. Synonymous variants: 149 observed, 174.46 expected, observed/expected ratio (o/e) 0.85, 90% interval 0.75 to 0.98.
Homologues: Orthologues: chimpanzee FBP2 (99% identical), pig FBP2 (98% identical), dog FBP2 (96% identical), guinea pig FBP2 (95% identical), rat Fbp2 (95% identical), mouse Fbp2 (94% identical), tropical clawed frog fbp2 (85% identical), macaque FBP2 (83% identical), zebrafish fbp2 (75% identical), Caenorhabditis elegans fbp-1 (61% identical), Drosophila melanogaster fbp (59% identical). Paralogues in human: FBP1 (76% identical).